BSG-AS1 (BSG antisense RNA 1)
Gene: Long non-coding RNA gene on chromosome 19 (562,360 to 572,404, reverse strand). Ensembl gene ENSG00000267751.
Diseases named in the same sentence as BSG-AS1 in open-access papers:
BSG-AS1 is named in the same sentence as 1 disease in open-access papers, as found by Europe PMC text mining. Sharing a sentence is not in itself a finding about the gene and the disease. The quoted sentences say what the papers report.
tumor (1 paper, 2022). "Like our analysis, LINC01554 may function as a tumor suppressor gene, while the CYTOR and BSG-AS1 may act as oncogenes." (PMID 35840618, 2022).